NPY (neuropeptide Y)
Diseases named in the same sentence as NPY in open-access papers (continued):
Sharing a sentence is not in itself a finding about the gene and the disease.
cancer (83 papers, 2008 to 2025). A tumor composed of atypical neoplastic, often pleomorphic cells that invade other tissues. "NPY signaling has also been implicated in numerous biological processes that are commonly deregulated over the course of cancer progression, including cell proliferation, immune cell function, fibrosis, neural invasion, and angiogenesis." (PMID 40073121, 2025). "The central orexigenic regulator NPY and its receptors have been implicated as growth-promoting factors in various cancer types." (PMID 35115550, 2022). "NPY encodes a neuropeptide, inhibiting its expression leads to increased cancer cell apoptosis, decreased exercise capacity, and changes in energy metabolism pathways." (PMID 34745098, 2021). "Neuropeptide Y (NPY) has been implicated in the regulation of cellular motility under various physiological and pathological conditions, including cancer dissemination." (PMID 33681186, 2020). "Anorexia in cancer cachexia is also strongly associated with chronic inflammation, which promotes the expression of pro-inflammatory cytokines in the hypothalamus, leading to the inactivation of NPY/AgRP neurons and activation of POMC/CART neurons." (PMID 37217930, 2023). "The possible causes of higher NPY expression include increased peptide production in cancer cells under the influence of external factors, e.g. nerve growth factor (NGF) from the nerves, or internal factors caused by transcriptional upregulation, as well as changes in methylation of the coding gene." (PMID 36583743, 2023). "In summary, understanding the role of NPY in whole-body energy balance could provide insight on mechanisms underlying the pathogenesis of cancer." (PMID 37051193, 2023). "In addition, NPY modulates cellular communication among other microenvironmental cells in prostate stroma, such as cancer-associated fibroblasts, immune cells and fibroblasts; with nerve fibres being the main source of NPY." (PMID 36583743, 2023). "Investigation of PYY and NPY, have collectively revealed that they are implicated in a variety of inflammatory disorders, such as autoimmune diseases, asthma, atherosclerosis, and cancer." (PMID 34572888, 2021). "Recent studies have indicated that NPY and its receptors are associated with human cancer." (PMID 25624911, 2015). "Neuropeptides like NPY and SP can amplify the activity of these factors, increasing nerve density and promoting cancer cell survival and drug resistance." (PMID 40805163, 2025). "This is consistent with studies that have found a role for NPY in regulating the motility and chemotaxis of cancer cells." (PMID 40073121, 2025). "Overall, these results suggest that enhanced neuronal activity under low BMI conditions promotes cancer cells proliferation and growth through the NPY/Y5R signaling axis in the brain during the early stages of metastatic colonization." (PMID 40595538, 2025). "The overexpression of NPY and its receptors in a variety of cancers provides a new research direction for targeted therapy." (PMID 41154659, 2025). "Specifically, we have elucidated the role of neuronal NPY in driving brain metastasis and highlighted its functional significance in regulating cancer cell survival and growth by reprogramming their metabolism." (PMID 40595538, 2025). "Using Oil-red O, a lipophilic dye that labels neutral lipids, we found a marked increase in the staining of lipid droplets in NPY-treated control cells compared to untreated or Y5rKO cancer cells." (PMID 40595538, 2025). "Simultaneously, inhibition of NPY signaling reduces the migration of cancer cells, promotes apoptosis, and alters energy metabolism." (PMID 41415714, 2025). "Our observations are consistent with other cancer types where NPY has been shown to play a role in metastasis." (PMID 40073121, 2025). "Similar to SP, NPY can also affect various cancers, such as PCa, BC, and neuroblastoma, and is generally assumed to be a growth‐promoting factor." (PMID 41415714, 2025).
cancer (continued). "The neuropeptide Y (NPY) system, best known for its role in controlling energy homeostasis, has also been shown to promote tumorigenesis in a range of cancer types, but its role in PC has yet to be explored." (PMID 40073121, 2025). "Consistent with SP, NPY also regulates cancer cells’ energy metabolism and promotes PCa cell proliferation by NF‐κB." (PMID 41415714, 2025). "We found a significant upregulation of FAO-driven OCR relative to glycolysis in NPY-treated control cells compared to untreated or Y5rKO cancer cells." (PMID 40595538, 2025). "Another group of neurotransmitters with auto- and paracrine functions, detected in cancer stroma, constitutes neuropeptides, such as neuropeptide Y (NPY), substance P, neurotensin, orexin/hypocretin, somatostatin, and vasoactive intestinal peptides." (PMID 39457647, 2024). "NPY plays a significant role in cancer development by mediating both proliferation and angiogenesis." (PMID 38375479, 2024). "NPY is a major co-transmitter in the sympathoadrenal system, released by nerve fibres that connect the cancer cell population with the neuroimmune–vascular environment by modulation of nutritional and inflammatory milieu." (PMID 36583743, 2023). "Using NPY/PYY/YRs expression/plasma levels as cancer biomarkers/prognostic factors requires more in-depth studies to confirm the findings reported in this section." (PMID 37373115, 2023). "The topographic analysis revealed a gradient of NPY system expression with immunoreactivity increasing towards the peripheral zone of cancer invasion." (PMID 36583743, 2023). "Morphological analysis revealed homogeneous membrane and cytoplasmic pattern of NPY staining in cancer cells and its membrane localization with apical accentuation in BP glands." (PMID 36583743, 2023). "Accordingly, an antitumor action is exerted with Y5R antagonists; however, NPY promoted, via Y1R/Y2R, an antinociceptive activity in cancer-induced bone pain." (PMID 37373115, 2023). "Novel 68Ga-labeled NPY, short analogs with potential applications in cancer imaging, have been developed." (PMID 37373115, 2023). "Among the 123 participants with CRC, there were 45 (37%) positive for SDC2/NPY methylation with a specificity of 96% among the non-cancer group using the LoD method." (PMID 37755164, 2023). "Botox particularly, but not only, suppresses NPY in cancer using in vitro models and tissues from a prior human chemical denervation investigation." (PMID 37051193, 2023). "High serum NPY levels correlate with relapse, metastasis, and poor survival, whereas a high Y5R expression has been suggested as a biomarker of angio-invasive cancer cells." (PMID 37373115, 2023). "Through its effects on energy homeostasis, the NPY system has complex and significant implications for the development of cancer." (PMID 37051193, 2023). "Current data show the peptidergic system’s high potential for cancer diagnosis, treatment, and support using Y2R/Y5R antagonists and NPY or PYY agonists as promising antitumor therapeutic strategies." (PMID 37373115, 2023). "This study showed that NPY, through dietary restriction, exerted an important role in cancer suppression and lifespan extension." (PMID 37373115, 2023). "Y2R expression was observed in undifferentiated cancer cells, and higher NPY levels have been reported in differentiated tumors, but these levels were lower in poorly differentiated tumors." (PMID 37373115, 2023). "In the Cancer Genome Atlas (TCGA) PAN-Cancer cohort, PCa exhibits the highest NPY expression among all examined cancers." (PMID 36583743, 2023). "The IDEGs (SLPI, IAPP, NPY, ISG15, PLA2G2A, and HLA-DMB) in the predictive PCa risk model constructed in the present study play an important regulatory role in cancer." (PMID 36774376, 2023). "NPY modulates not only tumor growth and vascularization but also the metastatic and chemoresistant phenotypes of cancer cells." (PMID 36499024, 2022).
cancer (continued). "Neuropeptide Y (NPY) and its receptors are expressed in various tumors and have multifaceted actions relevant to cancer biology, such as regulation of angiogenesis, cell proliferation, differentiation, survival, motility, and invasiveness." (PMID 35484119, 2022). "NPY receptors are overexpressed in different cancer entities —yet studies are sometimes contradictory and suggest a very context-specific role of NPY signaling in cancers other than EwS." (PMID 36497479, 2022). "NPY is a growth-enhancing factor in numerous cancers, including Ewing sarcoma, neuroblastoma, and breast and prostate cancer." (PMID 36499024, 2022). "The inhibition of cancer cell proliferation has been regulated by NPY-induced long-lasting ERK1/2 activation." (PMID 35011543, 2022). "Our study identified novel differentially methylated genes (mainly NPY and FAIM2) and also validated the previously identified differentially methylated CpG sites associated with PDAC cancer patient’s survival." (PMID 36329447, 2022). "In the heat map, NPY showed an obviously increasing expression in many cancer types, such as SARC, THCA, CHOL, PCPG, LUAD, LUSC, and LIHC." (PMID 35410586, 2022). "Immunostaining of SPINK1 was coincident with the defined cancer region and immunostaining of NPY was mostly localized to that of the PIN region." (PMID 29925878, 2018). "Our results indicate that ERG-rearrangements possibly induce metabolic changes in cancer cells by activating major metabolic signaling molecules such as NPY." (PMID 23390522, 2013). "Furthermore, to assess non–cancer cell–autonomous contributions of NPY signaling through NPY1R, we crossed the KPR172HC model with Npy1r−/− whole-body knockout mice." (PMID 40073121, 2025). "Therefore, targeting NPY and its receptors shows significant promise for advancing cancer therapeutics, with potential applications in both research and clinical applications." (PMID 41154659, 2025). "Neuropeptide Y can influence cancer cell proliferation and survival." (PMID 41301028, 2025). "Research on NPY's effects on aging, metabolic disorders, and cancer remains important." (PMID 41415714, 2025). "In conclusion, the neuropeptide Y/neuropeptide Y receptor system has conflicting roles in BC; further investigations are necessary to define its role in cancer pathogenesis, pending which analogs/antagonists could be used as appropriate for BC treatment." (PMID 41301028, 2025). "Additionally, conditioned media (CM) from ghrelin-treated primary neurons showed significantly higher NPY levels compared to controls or cancer cells." (PMID 40595538, 2025). "The observed reduction in the motility of KPR172HC cells upon BIBO3304 treatment suggests a role for NPY in cancer cell movement and could represent one of the modes through which NPY1R inhibition decreases metastasis to the liver." (PMID 40073121, 2025). "Many reports have suggested that the expression of peptides belonging to the NPY peptide family and their receptors could be used as biomarkers or prognostic factors in cancer." (PMID 37373115, 2023). "Moreover, 99mTc-labeled NPY short analogs showing Y1R affinity and potential applications in cancer imaging have been reported: in vitro studies demonstrated a specific cellular uptake and a high internalization rate, whereas the IC50 was 73.2 nM." (PMID 37373115, 2023). "Moreover, the involvement of pancreatic polypeptide (PP) and peptide YY (PYY), members of the NPY peptide family and less studied in cancer, will also be reviewed." (PMID 37373115, 2023). "Furthermore, NPY expression at the invasive cancer front was equal or higher than within ganglion cells." (PMID 36583743, 2023). "Excessive cytokine production in cancer also increases the expression of corticotrophin-releasing factor, a potent anorectic agent, which, in concert with prostaglandins, suppresses the production of NPY." (PMID 37217930, 2023).
cancer (continued). "In addition to the overall increase in NPY system expression in the cancer invasion areas, an enhanced immunoreactivity was observed around nerves and ganglia." (PMID 36583743, 2023). "Similarly, hypermethylation of SHISA3, KCNA3, NPY, and hypomethylation of NUMB, BST2, MAPK13 promoters, which have previously been implicated in other cancers, robustly separate normal and GBC-OSCC samples." (PMID 37245006, 2023). "The overexpression of NPY and its role in cancer progression could translate into cancer therapeutics, specifically through the use of NPYR antagonists, which have shown promising results for other diseases." (PMID 37264315, 2023). "In our analysis, we observed a strong NPY and Y2R immunoreactivity in angioinvasive cancer cells." (PMID 36583743, 2023). "The role of NPY and its receptors in cancer is not completely understood." (PMID 36497479, 2022). "Hyper-methylation of NPY is also observed in certain carcinomas." (PMID 36329447, 2022). "We checked if the parameters of cancer innervation depended on NPY expression." (PMID 34277455, 2021). "Whether this system plays a role in cancer-associated behavioral comorbidities remains to be determined, although early studies suggest that NPY and its receptors may play a significant role in cancer anorexia." (PMID 32193527, 2020). "Moreover, certain neuropeptides, including SP and NPY, play key roles in cancer progression." (PMID 41415714, 2025). "For example, patients with cancer might have poor appetite due to cytokine inhibition of neuropeptide Y. On the other hand, supplementation with n-3 PUFAs can decrease the production of interleukin-1 and interleukin-6 cytokines, then may combat the loss of appetite in these patients." (PMID 38281014, 2024). "In vitro and in vivo studies demonstrated that the optimized NPY conjugates were highly selective and effective in targeting cancer cells that overexpress NPY receptor, leading to increased uptake of boron-containing compounds and improved therapeutic efficacy in mouse models of cancer." (PMID 38961887, 2024). "Hence, the endothelial NPY can potentially promote cancer cell intravasation." (PMID 36583743, 2023). "In addition to ES, the expression of NPY and its Y5R has been shown in other cancers." (PMID 35484119, 2022). "This phenomenon may facilitate intravasation of cancer cells in NPY-rich tumors, such as NB." (PMID 33681186, 2020). "In the primary cancer samples, the expression of PCA3, ERG, NPY, and AMACR was significantly upregulated, making them the characteristic genes with the largest expression differences." (PMID 39988626, 2025). "Currently available data on the involvement of neuropeptide Y (NPY), peptide YY (PYY), and pancreatic polypeptide (PP) and their receptors (YRs) in cancer are updated." (PMID 37373115, 2023). "The increased NPY EI was also observed in PNI areas and overall expression levels were higher in cases with PNI, as compared to PNI-negative cancers." (PMID 36583743, 2023). "NPY has been negatively correlated with COL5A1, COL3A1, and COL4A1 collagen gene expressions in a pan-cancer study." (PMID 37373115, 2023). "In this section, the participation of NPY, PYY, and PP in the development of many cancer types is reviewed." (PMID 37373115, 2023). "The high NPY levels in PIN have been demonstrated previously, with a higher percentage of NPY-positive cells in high-grade PIN than in cancer." (PMID 36583743, 2023). "The first important aim that must be achieved is to perform a systematic study on the expression/role of NPY, PYY, PP, and their receptors in different types of cancers." (PMID 37373115, 2023). "The normal tissue samples in GTEx cohort had higher average expressions of both NPY and FAIM2 than in comparison with cancer samples in the TCGA cohort." (PMID 36329447, 2022).
cancer (continued). "The role of NPY in disease risk and progression remains unclear since it has been found that NPY genes may affect the risk of NHL, especially FL, but no significant changes in NPY levels after treatment have been revealed in patients with different types of cancer, including NHL." (PMID 36555171, 2022). "Substance P (SP) and neuropeptide Y (NPY), with their receptors of the GPCR superfamily, are the neuropeptides that have been studied the most in cancers." (PMID 36499024, 2022). "NPY-induced rapid and transient ERK1/2 activation was seen upon regulating the stimulation of cancer cell proliferation." (PMID 35011543, 2022). "In combined treatment with cisplatin, siRNAs against five genes (ADRA2A, F2RL3, NPSR1, NPY and TACR3) enhanced the anti-proliferation efficacy on cancer cells and reduced the self-recovery ability of surviving cells after the removal of the combined treatment." (PMID 36253428, 2022). "For the remaining gDMs (NPY, FOXE1, FAIM2, and KCNA6), we found hyper-methylation in PDAC, as confirmed by the higher extent of methylation in cancer samples." (PMID 36329447, 2022). "In fact, several cancer cells express receptors for a number of neuropeptides and neurotransmitters, like norepinephrine, epinephrine, dopamine, GABA, acetylcholine, SP and NPY which have stimulatory effects on migration of cancer cells." (PMID 29334991, 2018). "In contrast, other gene pairs, e.g. GRASP and NPY, or IRX1 and GRASP, or IRX1 and SDC2, are commonly methylated but show little correlation in measured levels of methylation within individual cancer samples." (PMID 24485021, 2014). "Selected targets were confirmed by immunohistochemistry: NPY and PLA2G7 (up-regulated in ERG+ cancers), and AZGP1 and TFF3 (down-regulated in ERG+ cancers)." (PMID 23390522, 2013). "We showed the potential of NPY, PENK, and WIF1 as combined epigenetic markers for CRC diagnosis, both in tissue and serum and tested their use as serum biomarkers in other cancers." (PMID 24289328, 2013). "For promoter-associated CpG islands, a number of them, including those of NTF3, FGF, OSR1, HOXA6, NPY and WT1, have previously been reported as differentially methylated in other cancer types." (PMID 20051947, 2010). "The knockout of Y5r did not affect cancer cell growth upon recombinant NPY treatment, as compared to scrambled knockout (ScrKO) control cells." (PMID 40595538, 2025). "Using primary KPR172HC cancer cells, we tracked cancer cell movement on CDMs upon pharmacological NPY1R inhibition using the NPY1R antagonist BIBO3304 to assess how inhibiting the NPY signaling axis might affect PC cell motility." (PMID 40073121, 2025). "In this study, we found that NPY is up-regulated at both the mRNA and protein levels in the highly metastatic KPR172HC model of PC relative to the normal pancreas and is predominantly colocalized with cancer cells in the primary tumor and liver metastases." (PMID 40073121, 2025). "Although the involvement of peptides in cancer is a promising line of research to develop specific antitumor therapeutic strategies, there is much to investigate regarding the participation of NPY, PYY, and PP in cancer progression: basic information on many tumors is scarce, incomplete, or absent." (PMID 37373115, 2023). "NPY immunoreactivity presented with various staining patterns, from membranous and polarized luminal in benign prostate cells to the cytoplasmic and membraneous in PIN and cancer." (PMID 36583743, 2023). "NPY promoted an antinociceptive effect that was inhibited with Y1R or Y2R antagonists (BIBO3304 and BIIEo246, respectively), and the peptide was upregulated in cancer-induced bone pain." (PMID 37373115, 2023). "NPY/Y1R system was also identified to inhibit forskolin-stimulated cAMP production and mobilize intracellular Ca2+ in MCF-7 cells, thus resulting in suppression of oestrogen-induced cancer cell proliferation." (PMID 35011543, 2022).